ATM (ATM serine/threonine kinase)
Diseases named in the same sentence as ATM in open-access papers (continued):
Sharing a sentence is not in itself a finding about the gene and the disease.
atherosclerosis (19 papers, 2014 to 2024). A disease characterized by the build-up of fatty material and calcium deposition in the arterial wall resulting in partial or complete occlusion of the arterial lumen. "Subjects with AT mutations have shown an elevated risk to develop atherosclerosis and its sequelae as shown by Su and Swift who observed elevated mortality risk for coronary heart diseases in subjects with ATM heterozygous deficiency." (PMID 39326070, 2024). "Individuals with ATM mutations are at increased risk of developing atherosclerosis, diabetes mellitus, heart failure, and coronary heart disease." (PMID 39326070, 2024). "Based on this understanding, studies of vascular function in humans harboring mutations in one allele of ATM prior to the development of atherosclerosis would be of great interest." (PMID 37787989, 2023). "ApoE−/− mice haploinsufficient for the DNA repair protein kinase ATM (ataxia telangiectasia mutated) show increased nuclear DNA damage and accelerated atherosclerosis." (PMID 36497101, 2022). "Although ATM is better characterized as a DDR gene, recent studies point out that defective ATM causes atherosclerosis and metabolic abnormalities." (PMID 36354755, 2022). "The antimalarial drug chloroquine activates the kinase ataxia telangiectasia mutated (ATM), improves metabolic syndrome and reduces atherosclerosis in mice." (PMID 31384309, 2019). "Concerning metabolic syndrome, atherosclerosis-prone apolipoprotein E (ApoE)(−/−) ataxia telangiectasia mutated (ATM)(+/−) mice were used to investigate the effects of a high-calorie diet on DNA damage and metabolic syndrome in the liver." (PMID 30513990, 2018). "It is currently known that humans with the heterozygous ATM mutation (ATM+/−), which account for 0.5–2% of the total population, also have an increase risk of developing atherosclerosis-related cardiovascular diseases." (PMID 24276232, 2014). "ATM deficient cells are characterized by hyperlipidemia, which promotes atherosclerosis and CVD, and several studies have associated ATM to CVD." (PMID 39187864, 2024). "APOE mice heterozygous for ATM display accelerated metabolic syndrome and atherosclerosis, indicating that genetic suppression of the ATM-AMPK pathway contributes to the development of dysfunction." (PMID 35196199, 2022). "This suggests a potential role for ATM in maintaining cardiovascular health through the protection against atherosclerosis and pathological cardiac remodeling." (PMID 31921839, 2019). "Via activation of ATM, long-term treatment of CQ protects against atherosclerosis, improves insulin sensitivity, and rescues glucose tolerance in type 2 diabetes (T2D)." (PMID 29717979, 2018). "Previous studies have suggested that defective ATM function promotes atherosclerosis through multiple systemic pro-atherosclerotic features, such as metabolic syndrome, oxidative stress, DNA damage and mitochondrial dysfunction." (PMID 24276232, 2014). "Therefore, we hypothesized that ATM mutations in ApoE−/− mice may lead to an overaccumulation of plasma ApoB-48-containing lipoproteins, thus promoting the development of atherosclerosis, which may be associated with the loss of or the impaired function of cytosolic ATM protein." (PMID 24276232, 2014). "Subjects with mutations in the Ataxia-Telangiectasia mutated (ATM) gene encoding for ATM kinase have a greater predisposition to develop atherosclerosis, but the mechanism behind this phenomenon is not yet understood." (PMID 39326070, 2024).
atherosclerosis (continued). "Taken together, Mercer and co-workers observed that ATM haploinsufficiency results in DNA damage in cells that compose atherosclerotic plaques, in addition to accelerating atherosclerosis in vivo, and inducing several features of metabolic syndrome and mitochondrial dysfunction." (PMID 36354755, 2022). "We tested the hypothesis that the anti-malarial drug chloroquine, which activates the kinase ATM, improves insulin sensitivity and decreases atherosclerosis in humans with metabolic syndrome." (PMID 31384309, 2019). "In the case of ApoE(−/−) ATM(+/−) mice, atherosclerosis was accelerated by a high-calorie diet." (PMID 30513990, 2018). "Moreover, in ATM+/− apoE−/− mice, atherosclerosis is attenuated by transplantation with ATM+/+ bone marrow." (PMID 28806901, 2017). "ApoE-deficient mice lacking protein kinase ATM (ataxia telangiectasia mutated), a protein pivotal in DNA damage detection, showed accelerated development of atherosclerosis." (PMID 27213333, 2016). "Interestingly, the old malaria drug Chloroquine (Aralen), a lysosomotropic agent that activates ATM signaling, was found to be capable of decreasing atherosclerosis and improving metabolic phenotype in mice." (PMID 25944698, 2015). "Previous studies have demonstrated that defective ATM function promotes atherosclerosis." (PMID 24276232, 2014). "Interestingly, ATM has emerged as a regulator of atherosclerosis and potentially angiogenesis." (PMID 31921839, 2019). "Atorvastatin therapy inhibited ATM and ATR and decreased VSMC senescence and apoptosis in atherosclerosis." (PMID 36156462, 2023). "The DNA damage kinase ATM is an upstream regulator of MDM2, and it does modulate the endothelial function, playing a role in atherosclerosis and angiogenesis." (PMID 31921839, 2019). "In mice, low dose chloroquine improves insulin sensitivity, decreases atherosclerosis, and suppresses activation of JNK in macrophages through pathways that require the presence of ATM." (PMID 31384309, 2019). "Arginase 1 (ARG1), ATM, and CD80 are elevated with various forms of cardiovascular disease including the following: vascular dysfunction, coronary artery disease, and atherosclerosis in obese individuals." (PMID 36437471, 2022).
head and neck squamous cell carcinoma (19 papers, 2008 to 2025). A squamous cell carcinoma that arises from any of the following anatomic sites: lip and oral cavity, nasal cavity, paranasal sinuses, pharynx, larynx, and salivary glands. "Somatic mutations of ATM and ATR were associated with higher HRD in BLCA, LUAD, CRC, PRAD, head–neck squamous cell carcinoma (HNSC), BRCA, and kidney renal clear cell carcinoma (KIRC) (FDR < 0.008)." (PMID 34572800, 2021). "Jian confirmed that Antisense inhibition of ATM gene enhanced the radiosensitivity of head and neck squamous cell carcinoma in mice." (PMID 21496344, 2011). "Zou and colleagues have shown that antisense inhibition of ATM gene enhances the radiosensitivity of head and neck squamous cell carcinoma in mice." (PMID 21496344, 2011). "Jian and colleagues have shown that antisense oligodeoxynucleotides of ATM enhances the radiosensitivity of head and neck squamous cell carcinoma in mice." (PMID 21496344, 2011). "On the contrary, ∆Np63α is rapidly phosphorylated by ATM and other kinases in head and neck squamous cell carcinomas (HNSCC) upon different treatments: this modification primes ∆Np63α for degradation to promote apoptosis of the damaged cells." (PMID 26668111, 2015). "Another study explored the effects of inhibiting ATM or ATR in conjunction with RT on head and neck squamous cell carcinoma (HNSCC)." (PMID 40565309, 2025). "Sidransky group found that kinases including ATM, CDK2, and p70s6K can phosphorylate ΔNp63α in HNSCC (head and neck squamous cell carcinoma) cells upon DNA damage." (PMID 24822180, 2014). "Moreover, overexpression of SET fails to induce up-regulation of ATM, BRCA1 and CHK2 and recruitment of BRCA2 to DNA damage foci in head and neck squamous cell carcinoma (HNSCC) lines upon cisplatin treatment, suggesting another important inhibitory role of SET on DNA damage repair." (PMID 36345878, 2022).
brain tumors (18 papers, 2011 to 2026). "In ATM GV carriers and their families, tumors of the brain (8/15 tumors, 53%), breast (2/15, 13%), neck, prostate, stomach, thyroid, and uterus (1/15, 7% each) were diagnosed." (PMID 41546701, 2026). "A search of the NIH ClinicalTrials.gov database for clinical trials on cell cycle checkpoint inhibitors in brain tumors identified two trials on inhibitors of ATM and CHK1, respectively, and five on the WEE1 inhibitor AZD1775." (PMID 35158967, 2022). "In this review, we summarize the knowledge in the field of brain tumor treatment with radiation therapy and cell cycle checkpoint inhibition via targeting ATM, ATR, CHK1, CHK2, and WEE1 kinases." (PMID 35158967, 2022). "Consequently, a brain-penetrant ATM inhibitor has entered clinical trials for adult brain tumors (NCT03423628)." (PMID 40244686, 2025). "ATM inhibition by KU-55933 leads to radiosensitization of GBM stem cells and GBM cells and reduced G2/M checkpoint arrest and DDR, underlining the role of these processes in the phenomenon of brain tumor radioresistance." (PMID 35158967, 2022). "Here, we discuss preclinical progress in molecular targeting of ATM, ATR, CHK1, CHK2, and WEE1, checkpoint kinases in the treatment of brain tumors, and review current clinical phase I-II trials." (PMID 35158967, 2022). "Cell cycle checkpoint inhibition is still in its infancy but while ATM, CHK1, and WEE1 inhibitors resulted in successful sensitization of various tumor types, including primary brain tumors, ATM and CHK2 inhibitors are less studied in brain tumors." (PMID 35158967, 2022). "In the following, the current knowledge of the effect of inhibition of ATM, ATR, CHK1, CHK2, and WEE1 kinases regarding the radiation treatment of brain tumors will be presented." (PMID 35158967, 2022). "More importantly, in both the brain tumour cells, KNS60 and ONS76, we observed a consistent decrease in the expression of gene coding for ATM and RAD50 proteins, which are involved in HR pathways." (PMID 25307264, 2014). "The treatment of malignant brain tumor cells by IR increased the phosphorylation of ATM and Chk2, but not that of ATR." (PMID 39273420, 2024). "And biomarkers such as MSI and ATM, which have been widely used in “hot tumors”, also seem to guide brain tumors that are not sensitive to immunotherapy." (PMID 35095931, 2021). "Moreover, bioinformatic analysis with the OncoFinder software against the complete “Cancer Genome Atlas” brain tumor gene expression dataset suggests the involvement of different proteins in the WNT and ATM pathways, and in Aurora B, Sem3A, and E-cadherin signaling." (PMID 28498803, 2017).
pancreatic ductal adenocarcinoma (18 papers, 2014 to 2025). An infiltrating adenocarcinoma that arises from the epithelial cells of the pancreas. "The synthetic lethality achieved with PARP1 inhibitors was also observed in pancreatic ductal adenocarcinoma cells with ATM mutation." (PMID 31192117, 2019). "Approximately 4% of all patients with pancreatic ductal adenocarcinoma have an underlying gene defect, with ATM, BRCA1/2, and PALB2 being the most commonly affected genes." (PMID 30736435, 2019). "Mutations in the serine/threonine kinase ataxia teleangiectasia mutated (ATM) have been linked to pancreatic ductal adenocarcinoma (PDAC) cohorts." (PMID 26220524, 2015). "However, one study has demonstrated that irinotecan-containing therapy improves PFS more than other treatment regimens in patients with pancreatic ductal adenocarcinoma harboring CHEK2/ATM mutations (germline/somatic)." (PMID 39858006, 2025). "Human TATDN2 was identified as a substrate for ATM in response to radiation in pancreatic ductal adenocarcinoma by phosphoproteomic analysis." (PMID 41404808, 2025). "ATM and WEE1 (DNA damage cell-cycle checkpoint protein) inhibition has been shown to decrease CXCR2 expression and surface PDL1 exposure in human pancreatic ductal adenocarcinoma (PDAC) cells with KRAS mutations." (PMID 38473997, 2024). "Pancreatic ductal adenocarcinoma (PDAC) is associated with accumulation of particular oncogenic mutations and recent genetic sequencing studies have identified ataxia telangiectasia-mutated (ATM) mutations in PDAC cohorts." (PMID 26220524, 2015). "Pathogenic germline ATM variants are frequently identified in patients with pancreatic ductal adenocarcinoma (PDAC) with and without a family history of the disease." (PMID 31963441, 2020). "Next, we conducted IHC staining of pancreatic ductal adenocarcinoma (PDAC) tissues using antibodies against ALDOA, ATM and PLK1." (PMID 34565365, 2021). "Biankin and colleagues provided evidence of frequent somatic ATM alterations in PDAC when they analyzed 99 pancreatic ductal adenocarcinomas without any family history using whole-exome sequencing." (PMID 31963441, 2020).
acute myeloid leukemia (17 papers, 2014 to 2025). Acute myeloid leukemia (AML) is a group of neoplasms arising from precursor cells committed to the myeloid cell-line differentiation. "Copy number gains of ATM in 3 out of 191 (1.6%) adult patients with de novo acute myeloid leukemia (AML) have been reported by the Cancer Genome Atlas Research Network." (PMID 28356161, 2017). "Furthermore, ATM is critically implicated in the pathogenesis of myelodysplastic neoplasms (MDS) and their progression to acute myeloid leukaemia (AML)." (PMID 40256842, 2025). "Interestingly, a recent study identified a fundamentally different type of anti-cancer pathway mediated by ATM in a MLL-AF9 driven acute myeloid leukemia model." (PMID 26030852, 2015). "Flow cytometry-based single cell network profiling (SCNP) was used to measure drug-induced activation of DNA damage response (DDR) proteins in cell lines with defined HRR pathway mutations (including ATM-/-, ATM+/-, BRCA1+/-, BRCA2-/-) and in primary acute myeloid leukemia (AML) samples." (PMID 24965603, 2014). "Previous studies showed indeed that FLT3-driven acute myeloid leukemia (AML) cells exposed to FLT3 inhibitors together with the inhibition of the ATM/G6PDH axis showed a higher response to therapy." (PMID 37932830, 2023). "ATM signaling ostensibly activates anti-apoptotic NF-kB signaling in an acute myeloid leukemia (AML) cell line, and treatment with the ATM inhibitor KU-55933 increased apoptosis." (PMID 38347838, 2024). "Interestingly, ATM−/− Gadd45a−/− mice not only showed a higher incidence of T-cell lymphoma compared to ATM−/− mice, but also developed acute myeloid leukemia (AML)." (PMID 24474198, 2014). "More interestingly, we also observed acute myeloid leukemia (AML) in ATM−/− Gadd45a−/− mice." (PMID 24474198, 2014). "(E) Model of ATM and mTOR-dependent survival of FLT3-ITD acute myeloid leukemia (AML) cells following FLT3 inhibition in BM microenvironment." (PMID 36259537, 2022).
head and neck cancer (17 papers, 2009 to 2024). A primary or metastatic malignant neoplasm affecting the head and neck. "ATM-deficient cells are susceptible to ionizing radiation; however, loss of one ATM allele or low ATM expression confers radioresistance to head and neck cancer (HNC) cells." (PMID 34068585, 2021). "Although the United States Food and Drug Administration has approved the use of ICB therapy for patients with head and neck cancer, the influence of ATM and ISG expression on the TIME and efficacy of ICB in oral cancer is unclear." (PMID 37174688, 2023). "The epigenetic alterations of CDKN2A (p16; located at 9p21), CDH1 (16q22.1), FHIT (3p14.2), RAR-β (3p24.2), and ATM (11q22.3) have been found to be related to clinical prognosis in cancer of the head and neck." (PMID 24782031, 2014). "The hypermethylation of CDH1 gene was considered to be a bad prognostic factor in tongue cancer and ATM gene hypermethylation was connected with poorer prognosis in head and neck cancers." (PMID 24782031, 2014). "However, in models where ATM is lost or not functional we observe the opposite effect, as demonstrated by the 32–79% reduction in phosphorylation of RAD50 in the ATM KO FaDu head-and-neck cancer xenograft model treated with AZD6738 for 24 h." (PMID 30385821, 2018). "Loss-of-function mutations in components of the ATM-mediated DNA damage response such as ATM, MRE11, and H2AX in tandem with overexpression of phosphatase Wip1, a negative regulator of this pathway, contribute to chemoresistance to crosslinking agents in head and neck carcinomas." (PMID 39095874, 2024). "Therefore, targeting ATM, ATR and DNA-Pk has been suggested as a strategy to potentiate the cell killing effects of radiotherapy through the inhibition of DNA DSB repair, particularly in solid tumors (e.g., head and neck cancers)." (PMID 32481544, 2020). "We also reported that patients with head and neck cancer without ICB therapy and with low ATM expression in their tumors exhibited poor OS rates." (PMID 37174688, 2023). "However, the role of ATM and BRCA1 gene expression in head and neck cancer (HNC) is not well characterized." (PMID 34068585, 2021).